HISLA (HIF1A stabilizing long noncoding RNA)
Synonyms: LINC01146
Gene: Long non-coding RNA gene on chromosome 14 (88,024,512 to 88,145,729, forward strand). Ensembl gene ENSG00000258867.
Diseases named in the same sentence as HISLA in open-access papers:
HISLA is named in the same sentence as 6 diseases in open-access papers, as found by Europe PMC text mining. Sharing a sentence is not in itself a finding about the gene and the disease. The quoted sentences say what the papers report.
breast carcinoma (7 papers, 2020 to 2025). "HISLA is overexpressed in both breast cancer tissues and patient serum and is significantly associated with advanced grade, histological grade, distant metastasis, and poor survival." (PMID 38505593, 2024). "Another example is HISLA (HIF-1α-stabilizing long noncoding RNA), which can be transmitted by extracellular vesicles from tumor-associated macrophages to breast cancer cells." (PMID 38505593, 2024). "Specifically, in breast cancer patients who exhibit PD or SD during treatment, HISLA expression levels were markedly greater than those observed in patients who achieved partial or complete remission." (PMID 39403606, 2024). "HISLA-mediated positive feedback between breast cancer cells and TAMs enhances aerobic glycolysis and chemoresistance of breast cancer." (PMID 38933287, 2023). "Serum HISLA expression in breast cancer patients was significantly increased compared to the healthy controls, which suggested lncRNA HISLA as a potential biomarker for breast cancer diagnosis and prognosis." (PMID 39280890, 2022). "Moreover, serum levels of HISLA were observed to decrease significantly after surgery, suggesting its potential as a biomarker for diagnosing and prognosticating breast cancer." (PMID 38505593, 2024). "Clinically, HISLA expression in TAMs was significantly correlated with therapeutic response and overall survival among breast cancer patients, indicating that HISLA is a potential prognostic biomarker and a valuable adjunct for guiding therapeutic decision-making." (PMID 39403606, 2024).
bladder cancer (1 paper, 2022). "Wnt/β-catenin signaling pathway has been proved to play crucial roles in the regulation of bladder cancer progression and contributes to EMT process; therefore, we investigated whether TAM exosomal lncRNA HISLA could regulate EMT ability of BC cells through Wnt/β-catenin signaling." (PMID 39280890, 2022).
tumor (12 papers, 2020 to 2025). "Reciprocally, the glycolytic product lactate upregulates the expression of HISLA in tumor-associated macrophages, which constitutes a feed-forward loop between TAMs and tumor cells." (PMID 34654454, 2021). "The use of aptamer-siRNA chimeras to mediate specific HISLA knockdown in TAMs to abort tumor glucose metabolism remodeling and restore antitumor immune functions warrants further investigation." (PMID 39539540, 2024). "Targeting the silencing of HISLA in TAMs to abrogate secretory HISLA in sEVs significantly impedes the ability of sEVs to induce resistance to apoptosis in tumor cells under chemotherapy." (PMID 39403606, 2024). "In turn, HISLA in macrophages is upregulated by lactate produced from glycolytic tumor cells, creating a feed-forward loop between tumor cells and tam." (PMID 39346921, 2024). "HISLA restrained the interaction between PHD2 and HIF‐1α to accelerate the accumulation of HIF‐1α and the release of lactic acid from tumor cells, which in turn up‐regulated HISLA in macrophages as a positive feedback loop." (PMID 36599655, 2023). "In turn, the lactic acid released by glycolytic tumour cells upregulates HISLA expression in macrophages, forming a feed-forward loop." (PMID 35801079, 2022). "Thus, HISLA silencing mediated by RNA interference has great potential to interrupt tumor glucose metabolic reprogramming, which will further weaken TME immunosuppression induced by tumor metabolic reprogramming and help restore immune cell function." (PMID 39539540, 2024). "Moreover, elevated HISLA expression serves as a valuable indicator for assessing tumor histological grade, clinical stage, lymph node metastasis, and HER2 subtypes." (PMID 39403606, 2024). "Furthermore, we performed in vivo metastatic and xenograft experiments, and we found that silencing of HISLA significantly alleviated lung metastasis of tumor cells and suppressed tumor development." (PMID 39280890, 2022). "Mechanistically, lactate emitted by glycolytic breast cancer cells induced HISLA upregulation in TAMs via ERK-ELK2 signaling, which was then released in the tumor microenvironment in extracellular vesicles and taken up by tumor cells." (PMID 32640630, 2020).
cancer (7 papers, 2020 to 2025). A tumor composed of atypical neoplastic, often pleomorphic cells that invade other tissues. "This study demonstrates that RNA-interference-mediated silencing of HISLA may be a potentially powerful means to inhibit glycolytic processes in cancer cells, and they demonstrate that targeting TAMs-specific lncRNAs has great potential in cancer therapy." (PMID 36741380, 2022). "Glucose transporters (GLUTs) as important modulators of glucose utilization which are commonly dysregulated in cancer, have been shown to be targeted by several lncRNAs such as LINC01638, Ftx, XIST, YIYA (LINC00538), HISLA, AWPPH, and UCA1." (PMID 33123468, 2020).
HISLA also shares sentences with these, for which no sentence is quoted: hepatocellular carcinoma (2 papers); prostate carcinoma (1).